ENSG00000284969 (novel protein)
Gene: Protein-coding gene on chromosome 11 (33,698,261 to 33,722,467, reverse strand). Ensembl gene ENSG00000284969.
Genetic constraint (gnomAD): Loss-of-function variants: 8 observed, 9.15 expected, observed/expected ratio (o/e) 0.87, 90% interval 0.51 to 1.55. That is too few expected variants to judge how well the gene tolerates losing a copy. Missense variants: 97 observed, 111.57 expected, observed/expected ratio (o/e) 0.87, 90% interval 0.74 to 1.03. Synonymous variants: 47 observed, 50.4 expected, observed/expected ratio (o/e) 0.93, 90% interval 0.74 to 1.19.